BANF1 (barrier to autointegration nuclear assembly factor 1)
Diseases named in the same sentence as BANF1 in open-access papers (continued):
Sharing a sentence is not in itself a finding about the gene and the disease.
cancer (16 papers, 2015 to 2025). A tumor composed of atypical neoplastic, often pleomorphic cells that invade other tissues. "Disease Ontology (DO) analysis demonstrated that BANF1 is linked to various human diseases, including gastrointestinal disorders and malignant tumors." (PMID 40384864, 2025). "Gene Set Enrichment Analysis (GSEA) of pan-cancer data identified BANF1's association with the Hedgehog pathway, epithelial-mesenchymal transition (EMT), DNA repair, and apoptosis in COAD and READ." (PMID 40384864, 2025). "Diagnostic values of VRK1 and BANF1 in various cancers were assessed using ROC analysis." (PMID 40384864, 2025). "Despite its upregulation is often associated with cancer development and cancer cell proliferation and migration, in in vivo SMCs, BANF1 upregulation might increase resistance to vessel mechanical stress by playing a critical role in nuclear rupture repair." (PMID 37570694, 2023). "Our investigation successfully identified three signature genes implicated in GC, with a specific focus on the barrier to autointegration factor 1 (BANF1), which exhibits elevated expression across various cancer types, including GC." (PMID 38261746, 2024). "We conducted a thorough analysis of BANF1 expression across all cancer types within the TCGA database." (PMID 38261746, 2024). "There are very few studies on the mechanism of action of BANF1 in cancer, and most of the studies have only included expression- and cellular-level studies." (PMID 38261746, 2024). "Knockdown of BANF1 expression in cancer cells genetically induces activation of innate immunity through the cGAS/STING pathway." (PMID 39439799, 2024). "Our study, based on TCGA database, revealed substantial overexpression of BANF1 in more than a dozen different cancer types, including GC." (PMID 38261746, 2024). "Our comprehensive analysis, which incorporated data from the TIMER2 databases, revealed distinct and tumor-specific expression patterns of BANF1 in 33 different cancer tissues." (PMID 39439799, 2024). "Banf1 protein also was observed to accumulate at sites of nuclear envelope rupture in the context of cancer cell migration and deformation through tight interstitial spaces." (PMID 32156810, 2020). "The inhibitory effect of miR-203 on the cancer cells is partially mediated by downregulating its target, BANF1, since knockdown of BANF1 also suppresses colony formation, migration and invasion." (PMID 25658920, 2015). "Although BANF1 is linked to the development and progression of various cancers, its role and mechanisms in CRC have not been investigated." (PMID 40384864, 2025). "Banf1 upregulation has been demonstrated in several cancer subtypes, including breast tumours." (PMID 40664994, 2025). "Furthermore, a correlation between BANF1 and the prognosis of certain types of cancer has been shown." (PMID 39439799, 2024). "To confirm the cancer-causing role of BANF1 in HNSCC, we initially examined BANF1 mRNA expression." (PMID 39439799, 2024). "Therefore, suggesting that the abnormal nuclear phenotype observed after Banf1 depletion may induce growth inhibiting effects on tumour cells or heighten their sensitivity to existing anti-cancer therapeutics." (PMID 40664994, 2025). "By using mass spectrometry-based quantitative proteomics analysis, we discovered that strophanthidin (SPTD) upregulated 24 proteins, including Banf1 and LAMN, and downregulated 35 proteins, such as SRSF3 and COL1A5, in A549 cancer cells." (PMID 38398629, 2024). "In conclusion, these gene enrichment studies suggest that BANF1 is important in the immune response of HNSCC, as well as in the invasion of cancer cells through the cell adhesion pathway." (PMID 39439799, 2024). "However, the exact molecular mechanism of BANF1 involvement in cancer remains unclear." (PMID 38261746, 2024).
cancer (continued). "Barrier-to-autointegration factor 1 (BANF1) is an abundant and ubiquitously expressed postnatal mammalian protein that is overexpressed in numerous human cancers and can promote cancer cell proliferation." (PMID 39439799, 2024). "Here, we define a novel role for Banf1 in TNBC and as a potential anti-cancer therapeutic target." (PMID 40664994, 2025). "Additional research is needed to determine whether inhibition of BANF1 can effectively suppress the malignancy of HNSCC cells, in terms of proliferation, migration, and invasion, which are the primary characteristics of cancer cells." (PMID 39439799, 2024).
tumor (12 papers, 2014 to 2025). "The results demonstrated a significant upregulation of BANF1 mRNA levels in CRC compared to adjacent non-tumor tissues." (PMID 40384864, 2025). "Tumors from the BANF1 knockdown group exhibited higher cleaved-caspase-3 staining intensity, indicating increased apoptosis among tumor cells." (PMID 40384864, 2025). "Although our study is the first to demonstrate Banf1’s role in tumour cell proliferation, dysregulated expression of several Banf1-interacting, NE-localised proteins, including Man1 and Ankle2, have been correlated with tumour cell proliferation." (PMID 40664994, 2025). "Thereby, indicating the importance of maintaining the NE equilibrium for cell growth regulation and providing potential insight into the mechanism by which Banf1 depletion impedes tumour cell viability." (PMID 40664994, 2025). "A study 24 used IHC to evaluate BANF1 protein expression, revealing significantly elevated BANF1 levels in tumor tissues compared to adjacent non-tumor gastric mucosa." (PMID 40384864, 2025). "The initial evidence for Banf1’s role in tumourigenesis was as a potential biomarker for tumour prognosis in gastric and oesophageal cancer." (PMID 40664994, 2025). "To elucidate the influence of BANF1 expression on tumorigenesis and tumor growth, we performed in vivo experiments using a cell line-derived xenograft (CDX) model." (PMID 38261746, 2024). "A recent study exploring the role of BANF1 in tumor immunity revealed that the knockdown of BANF1 increased immune cell infiltration into the tumor microenvironment." (PMID 38261746, 2024). "Multiple studies have demonstrated that BANF1 is related to the growth, infiltration, and spread of various tumor cells, such as in gastric, liver, breast, esophageal, and cervical malignancies." (PMID 39439799, 2024). "In this model, both the control and experimental groups received injections of MKN-45 cells treated with sh-NC and sh-BANF1, respectively, enabling a meticulous assessment of subcutaneous tumor development." (PMID 38261746, 2024). "The oncogenic effect of BANF1 knockdown was established using wound healing tests, Transwell invasion assays, and tumor formation assays in nude mice." (PMID 39439799, 2024). "Subcutaneous injection of BANF1-stabilized and BANF1 knockdown cells SCC9 cells were used to evaluate tumor formation in nude mice." (PMID 39439799, 2024). "Based on the results acquired, BANF1 mRNA levels in tumor tissues were significantly higher than those of healthy tissues." (PMID 39439799, 2024). "Banf1 depletion inhibited proliferation and induced mitotic arrest in TNBC cells via loss of nuclear envelope integrity and aberrant nuclear morphology, inducing TNBC tumour cell-specific cell death." (PMID 40664994, 2025). "In addition, we explored the link between BANF1, drug sensitivity, and the tumor immune microenvironment." (PMID 39439799, 2024). "BANF1 is a crucial factor for cell growth and may play a role in tumor development and the transition of normal cells into cancerous cells." (PMID 39439799, 2024). "This confirms the role of BANF1 in promoting tumor growth in HNSCC." (PMID 39439799, 2024). "The relationship between tumor immune cell infiltration and BANF1 expression were also examined." (PMID 39439799, 2024). "Furthermore, immunohistochemical staining of mouse tumors provided deeper insights into the influence of BANF1 on tumor proliferative capacity." (PMID 38261746, 2024). "Moreover, our in vivo experiments using nude mouse models revealed a notable impediment in tumor growth following BANF1 knockdown." (PMID 38261746, 2024). "Finally, functional in vitro and in vivo assays were used to explore the effects of BANF1 on tumor growth and metastasis of HNSCC." (PMID 39439799, 2024).
tumor (continued). "In addition, western blot analysis showed that expressions of BANF1 was elevated in 15 out of 20 paired (75%) tumor tissues (T) than in normal (N) cervical tissues." (PMID 25658920, 2015). "Thereby, suggesting that Banf1 depletion may specifically suppress tumour cell growth." (PMID 40664994, 2025). "Together with the data from the current study, this suggests that in addition to inhibiting tumour cell growth directly, inhibiting Banf1 may also synergise with immune checkpoint blockade in tumours with upregulated Banf1 levels to offer new opportunities for tumour therapy." (PMID 40664994, 2025). "In summary, aberrant nuclear morphology has been linked to disruption of cellular processes including migration, cell cycle progression, mitosis, and chromatin organisation highlighting the diverse mechanisms by which Banf1 depletion may impair tumour cell growth." (PMID 40664994, 2025). "This suggests that increased BANF1 expression may inhibit anti-tumor immune responses within GC." (PMID 38261746, 2024). "Lastly, we investigated whether BANF1 affects tumor growth and metastasis in HNSCC." (PMID 39439799, 2024). "The study demonstrated elevated mRNA and protein expression levels of BANF1 and VRK1 in tumor tissues relative to adjacent normal tissues." (PMID 40384864, 2025). "In subcutaneous tumor models using nude mice, BANF1 silencing in CRC cells led to significantly smaller tumors and reduced tumor weight compared to controls (p < 0.01)." (PMID 40384864, 2025). "Although we conducted ex vivo and in vivo experiments to demonstrate the tumor-promoting effects of BANF1 in HNSCC, additional trials are required to fully elucidate the role and mechanism of BANF1 in HNSCC." (PMID 39439799, 2024). "As Banf1 was upregulated at the RNA and protein levels in the TNBC cells examined, and abnormal NE features are characteristic of tumour cells, we next determined whether Banf1 NE localisation was disrupted in TNBC cells." (PMID 40664994, 2025). "We also demonstrate Banf1’s essential role in maintaining TNBC nuclear morphology and proliferation, highlighting the potential for a role of Banf1, and the nuclear envelope, in tumour cell growth." (PMID 40664994, 2025). "The analysis revealed that in the training set, the expression of BANF1, CDK2AP2, DDT, LRIG1, MRPL4, and S100A13 was significantly upregulated in tumor samples, and the expression of EPS8, NUCB2, PAF1, PMP22, RABGAP1L, and USO1 was higher in control samples (p < 0.05)." (PMID 41000388, 2025). "Collectively, this suggests that the tumour cell proliferation is unlikely to be exclusively mediated by the degree of Banf1 upregulation, although further analysis using larger sample sizes is required for validation." (PMID 40664994, 2025). "Consistent with our bioinformatics analysis, densitometry analysis demonstrated significantly elevated Banf1 intensity in all tumour cell lines examined compared to non-malignant MCF10A control cells." (PMID 40664994, 2025). "We evaluated the precision of BANF1 as a predictor of treatment outcome in five cohorts of patients with HNSCC treated with ICB and contrasted it with other established biomarkers related to tumor immune evasion." (PMID 39439799, 2024). "Our analysis, based on the TCGA database, indicated a negative correlation between elevated BANF1 expression in GC tumor tissues and immune cell infiltration within these tissues." (PMID 38261746, 2024). "However, Banf1’s role in tumour cell survival and the therapeutic potential of targeting Banf1 has not been previously determined." (PMID 40664994, 2025). "Moreover, we demonstrated that cytoplasmic p16 interacted with CDK4 and other unreported proteins, such as BANF1, AKAP8 and AGTRAP, which could sequester p16 to avoid nuclear translocation, and then, impair its anti-tumor function." (PMID 32204550, 2020).
tumor (continued). "In addition, Banf1 depletion induces TNBC mitotic arrest and cell death, suggesting that targeting Banf1 may improve TNBC treatments by providing a novel mechanism to specifically inhibit tumour cell growth." (PMID 40664994, 2025).
infection (8 papers, 2014 to 2025). The state of being infected such as from the introduction of a foreign agent such as serum, vaccine, antigenic substance or organism. "BAF was depleted in TREx-BCBL1-RTA cells via infection with lentiviruses encoding two independent shRNAs targeting BANF1 transcripts prior to reactivation." (PMID 36746947, 2023). "Loss of Banf1 expression was associated with reduced infection of RNA and DNA viruses, and the enhanced expression of ISGs was mediated by a pathway requiring cGAS, STING, and IRF3." (PMID 32156810, 2020). "Multistep growth curve analysis showed that a deficiency of Banf1 was associated with less infection by HSV-1 and WNV-Kunjin compared to control cells." (PMID 32156810, 2020). "The proviral function of BANF1 has already been described in the context of infection by various retroviruses such as HIV (Human Immunodeficiency Virus) or MoMLV (Moloney Murine Leukemia Virus), with BANF1 being part of their pre-integration complex." (PMID 40707000, 2025). "When SLK cells were treated with BANF1 or NTC siRNA prior to infection with rKSHV.219, the cGAS expression of BANF1 siRNA transfected cells was increased compared to NTC." (PMID 36746947, 2023). "Thus, detection of BANF1 may have failed because critical epitopes detected by the anti-BANF1 monoclonal antibody might have been masked by post-translational modifications induced on BANF1 in response to the infection, thereby preventing recognition by the antibody." (PMID 40707000, 2025). "Next, WSL cells were transfected with either 3 nM or 6 nM si-BANF1 for 24 h, inoculated with ASFV at a multiplicity of infection (MOI) of 1, and the infection was allowed to proceed for 0, 24, or 48 h." (PMID 40707000, 2025). "Reciprocally, ΔBanf1 + Banf1 complemented BV2 cells, which had lower levels of ISG mRNA at baseline, showed greater infection with WNV-Kunjin and SINV-EEEV." (PMID 32156810, 2020). "Reciprocally, ectopic expression of Banf1 resulted in lower ISG levels at baseline and greater WNV-Kunjin and SINV-EEEV infection." (PMID 32156810, 2020). "We observed no significant changes in BANF1 protein abundance throughout the course of the infection, indicating that BANF1 is not undergoing ASFV-induced degradation." (PMID 40707000, 2025). "To evaluate further the effect of Banf1 expression on the basal or rapidly induced ISG response, we analyzed viral replication under inoculation conditions with high and low multiplicities of infection with SINV-EEEV and VSV." (PMID 32156810, 2020).
neurological diseases (2 papers, 2023 to 2024). "Pathogenic variants in VRK1, a gene encoding serine/threonine kinase that phosphorylates BAF, causes neurological disorders ranging from pontocerebellar hypoplasia clinical similarities of BANF1-related disease to dHMN with (MIM#607596, #620542)." (PMID 38274568, 2024).
gastrointestinal tumors (1 paper, 2025). "Recent studies have investigated the relationship between BANF1 and gastrointestinal tumors." (PMID 40384864, 2025).
BANF1 also shares sentences with these, for which no sentence is quoted: cardiomyopathy (3 papers); lipodystrophy (3); Emery-Dreifuss muscular dystrophy (2); esophageal cancer (2); hepatocellular carcinoma (2); Hutchinson-Gilford progeria syndrome (2); prostate carcinoma (2); restrictive dermopathy (2); acquired lipodystrophy (1); B-cell lymphomas (1); brain disorder (1); breast tumours (1); clear cell renal carcinoma (1); colorectal adenocarcinoma (1); Crohn disease (1); Ewing sarcoma (1); Fanconi anemia (1); gastrointestinal disorders (1); genetic disorders (1); glioma (1); Insulin resistance (1); Intellectual disability (1); invasive breast carcinoma (1); ischemia reperfusion injury (1); malaria (1); microcephaly (1); multiple lipomatosis (1); muscular dystrophy (1); neurodegenerative disease (1); neuropathies (1).
A further 5 diseases each share a sentence with BANF1 in 1 paper.